EGF (epidermal growth factor)
Diseases named in the same sentence as EGF in open-access papers (continued):
Sharing a sentence is not in itself a finding about the gene and the disease.
breast carcinoma (continued). "Moreover, EGF seems to induce an inhibition of proliferation through the stimulation of an interleukin 6 type cytokine, oncostatin M, in both estrogen receptor positive and negative breast cancer cells." (PMID 26258011, 2015). "Importantly, this conclusion is not restricted to transformed keratinocytes, as EGF-mediated Src, -MEK1, -ERK1/2 and -STAT3 phosphorylations were also severely impaired on KIAA1199 deficiency in breast cancer-derived MCF7 and SK-BR-3 cells, as well as in immortalized breast epithelial NMuMG cells." (PMID 25366117, 2014). "Likewise, MDA-MB-435-Hyg breast cancer cells did not respond to EGF stimulation." (PMID 22487193, 2012). "However, it should be noted that the growth medium DFCI-1 used for the normal human mammary epithelial cells contains additional growth factors that are not presented in the medium for maintaining the breast cancer cells, which include EGF, estradiol, and insulin." (PMID 22494620, 2012). "On the other hand, we did not detect impairment of Ser473 Akt phosphorylation in breast cancer cells stimulated with epidermal growth factor upon downregulation of PLCγ1 suggesting that the role of PLCγ1 in mediating Akt phosphorylation may be cell and stimulus specific." (PMID 20011604, 2009). "Our results showed that stimulation of breast cancer cells with BEC (hCMEC/D3)-conditioned media but not control media (MEM or EC M), stimulated EGFR phosphorylation to levels similar to those of EGF stimulation." (PMID 38762624, 2024). "Serum levels of EGF, G-CSF, TNFα, Groα, IP10, MIP-1b, MDC, VEGFα, TGFβ1, and TGFβ2 were also high in women with breast cancer compared to the control group (no cancers)." (PMID 38541912, 2024). "In non-stimulated, highly invasive breast cancer cells, ARF1 is partially localized to dynamic plasma membrane ruffles where epidermal growth factor (EGF) stimulation promotes its rapid and transient activation." (PMID 35805075, 2022). "We evaluated the levels of TGF-β, EGF, FGF, DLL4, and VEGF in the peripheral blood and WF of breast cancer patients in the IORT and non-IORT groups." (PMID 35681234, 2022). "Our data suggest that AKT3 plays a crucial role in the steps of breast cancer metastasis as knockdown of AKT3 in bone-seeking breast cancer cells increases migration, invasion, and chemotaxis towards EGF without affecting cell proliferation." (PMID 33670586, 2021). "The CELx HSF test was used to determine the amount of HER2 participation in NRG1b- and EGF-driven activity in the HER2+ (n = 9) and HER2- (n = 10) breast cancer cell lines in the presence and absence of pertuzumab." (PMID 28302091, 2017). "The PI3K/Akt inhibitor Ly 294,002, but not the ERK inhibitor PD 98059, inhibits the EGF-stimulated increase in m-SREBP-1 and FASN protein levels in MDA-MB-231 human breast cancer cells." (PMID 29282029, 2017). "Previous study demonstrated that HRG, but not EGF, can induce phenotypic changes in MCF-7 breast cancer cells." (PMID 25643809, 2015). "To distinguish between hard-wired isoform ratios and inducible promoter switching, we applied EGF or GW2974, a dual EGFR/ErbB-2 kinase inhibitor, on MCF10A cells, on another non-tumorigenic mammary cell line, and on nine breast cancer lines." (PMID 24324612, 2013). "This is not surprising in view of the fact that in MCF-7, MCF-10, and MDA-MD-231 breast cancer cells, LOX, but not COX inhibitors, blocked EGF/transforming growth factor-α stimulation of 12-HODE and 13-HODE production and cellular proliferation." (PMID 18087590, 2007). "In MCF-7, MCF-10, and MDA-MB-231 human breast cancer cells, LOX, but not COX, inhibitors block EGF/transforming growth factor α stimulation of 12-HODE, and 13-HODE production and cellular proliferation." (PMID 16330350, 2005).
breast carcinoma (continued). "In this study, we investigate the distinct behaviors of gene expression dynamics in MCF-7 breast cancer cells under two stimuli: heregulin (HRG), which promotes cell fate transitions, and epidermal growth factor (EGF), which binds to the same receptor but fails to induce cell-fate changes." (PMID 40430050, 2025). "TGF-β or EGF on HER2-overexpressed breast cancer cells can induce SMAD3 phosphorylation, and CEACAM6 expression level is upregulated after treatment, but this correlation is not obvious in HER2-negative breast cancer cells." (PMID 38796667, 2024). "Breast cancer MDA-MB-231 and MDA-MB-468 lines were treated with H182 for 2 h at concentrations of 0–3 μM that inhibit constitutive and ligand-induced Stat3 activation, stimulated or not with EGF for 12 min, and whole-cell lysates were prepared." (PMID 35276290, 2022). "Interestingly, among the fourteen breast cancer cell lines, these four cell lines alone did not express EGFR or were insensitive to EGF activation, suggesting a specific role for this receptor." (PMID 36380366, 2022). "Moreover, in the breast cancer cell line MDA-MB-231, EGF was shown to promote mesenchymal rather than amoeboid migration." (PMID 33777943, 2021). "Without EGF (epidermal growth factor) stimulation, JAK- and Src-mediated constitutive activation of STAT3; upon EGF stimulation, EGFR kinases induced maximal activation of STAT signaling in breast cancer cells." (PMID 34199002, 2021). "Finally we examined EINCR1 expression in two breast cancer cell lines and showed that, similar to FOS, it is inducible by EGF stimulation in MCF7 cells but not in MDA-MB-231 cells." (PMID 28732076, 2017). "Firstly, to construct a breast cancer EMT cell model, we applied TGF-β1 and EGF/bFGF to induce EMT and found that none of the breast cancer cell lines could undergo a TGF-β1 (5–10 ng/ml)-induced EMT." (PMID 27124117, 2016). "Luminal breast cancer cells usually do not exhibit amplification of the EGF-signaling HER2 receptor or show only low over-expression of this receptor; nevertheless, they bind EGF and respond to its tumor-promoting stimuli." (PMID 24369447, 2013). "Here we show that in MDA-MB-468 breast cancer cells, both ORAI1 and TRPC1 silencing reduce non-stimulated Ca2+ influx; suggesting that altered activity of these channels may be a feature of EGF-induced EMT." (PMID 22666335, 2012). "Elongation assays showed that, like DOCK4-depleted cells, cells lacking either DOCK9 or CDC42 did not elongate upon EGF stimulation as control cells, suggesting that DOCK9 and CDC42, together with DOCK4 and RAC1, are essential for the elongation and subsequent intercalation of breast cancer cells." (PMID 38762624, 2024). "GPER, which is considered as a negative prognostic marker in breast cancer, has been shown previously to be upregulated and/or activated by a plethora of stimuli classically involved in HIF-1 pathway, including hypoxia, EGF, IGF1, insulin and the metals copper and zinc." (PMID 29212519, 2017). "Furthermore, unlike in breast cancer cells, LIP protein and C/EBPβ activity upon EGF stimulation were unchanged in lung adenocarcinoma cell lines, indicating that C/EBPβ may not be involved in proliferation in response to growth factor stimulation." (PMID 25767874, 2015). "In addition to this, it was recently shown that the EGF-induced cell migration of EGFR/c-erbB-2-positive breast cancer cells, but not of solely EGFR-positive breast cancer cells, could be blocked with moderate concentrations of the PLC-γ1 inhibitor U73122." (PMID 14710234, 2004).
lung carcinoma (273 papers, 1992 to 2026). "For instance, A549 cells harbor a k-RAS mutation and cannot be used to represent lung cancer cells with EGF mutations." (PMID 38188678, 2023). "EGFR gene mutation is a form of the gene variant that frequently occurs in lung cancer, resulting in an overactivated EGF signal that stimulates abnormal cell growth and tumorigenesis." (PMID 36770773, 2023). "Lung cancer is the leading cause of cancer mortality worldwide, and most of the patients after treatment with EGF-TKIs develop drug resistance, which is closely correlated with EMT." (PMID 35183200, 2022). "This study aims to investigate the antitumor effects of AvnA and C on lung cancer cell models treated with EGF and the molecular mechanisms underlying the antitumor activity." (PMID 35955669, 2022). "GMI inhibits epidermal growth factor (EGF)-induced metastasis through autophagy signaling and cause the cell death in lung cancer cells." (PMID 33382817, 2020). "Here, we aimed to evaluate the predictive and prognostic role of EGF+61A>G SNP in lung cancer from Brazilian EGFR‐mutated TKI‐treated patients." (PMID 32881389, 2020). "EGF-induced nuclear EGFR localization in DUOX1-deficient lung cancer cells was associated with altered dynamics of cysteine oxidation of EGFR, and an overall reduction of EGFR cysteines." (PMID 30890751, 2019). "One study reported that epidermal growth factor (EGF) mediated activation of telomerase activity in lung cancer is linked to the binding of ETS-2 to hTERT promoter." (PMID 29364142, 2018). "Previous study showed that GPRC5A deficiency leads to dysregulated STAT3 signaling via EGF-EGFR pathway in lung cancer." (PMID 28270740, 2017). "In lung cancer, a tight cooperation between the EGF/EGFR and mPGES-1 causes an enhanced tumorigenisis." (PMID 29246166, 2017). "It has recently been reported that epidermal growth factor (EGF)-mediated activation of telomerase activity in lung cancer is associated with direct binding of ETS-2 to the hTERT promoter." (PMID 27323951, 2016). "It is noteworthy that lung cancer cells depleted of Vav1 also showed a decrease in EGF and TGFα, further highlighting the association between Vav1 expression in cancer cells and the expression of autocrine/paracrine growth factors." (PMID 26353933, 2015). "The variant carriers of EGF:rs2237051 have been reported to be associated with a markedly decreased risk of lung cancer." (PMID 24945674, 2014). "In Portugal, several studies have assessed the role of epidermal growth factor and its receptor regulation with respect to cancer susceptibility for gliomas, gastric cancer and lung cancer." (PMID 24516537, 2014). "In our model, we confirmed that EGF-driven EMT was reversible in EGFR mutated TWIST1 expressing lung cancer cells." (PMID 22272264, 2012). "Additionally, by considering smoking—one of the most common etiological factors of lung cancer—this research further investigates the association between young lung adenocarcinoma and EGF gene polymorphisms, as well as environmental factors." (PMID 40696566, 2025). "As the AKT/mTORC1 signaling is a crucial signaling axis downstream of EGF receptor which has high mutation rate in lung cancers, we asked whether C1orf74 has any role in EGF-stimulated activities of AKT and mTORC1 in LUAD cells." (PMID 36032960, 2022). "Further research is needed to determine whether baseline serum EGF levels could serve as a diagnostic biomarker in head and neck or lung cancer patients." (PMID 34115785, 2021). "The polymorphism in the EGF promoter region EGF+61A>G (rs4444903) has been associated with cancer susceptibility, but its role in lung cancer patients treated with tyrosine kinase inhibitors (TKIs) remains unknown." (PMID 32881389, 2020). "To further investigate the mechanism underlying the effect of NEDD4 on EGF-stimulated lung cancer cell migration, we first examined whether NEDD4 is in the EGFR signaling complex." (PMID 29455656, 2018).
lung carcinoma (continued). "Back to EGF+61 genetic polymorphisms and lung cancer risk: looking to the future!" (PMID 25628210, 2014). "Importantly, constitutive activation of EGFR or enhanced EGF signaling is frequently found in different types of cancers, especially in lung cancer, where it is associated with cancer initiation, tumor growth/progression, metastasis and poor prognosis." (PMID 24849319, 2014). "One of the most important growth factors associated with lung cancer is the EGF." (PMID 25109354, 2014). "Lower levels of EGF, IL-15, and IL-1ra may be involved in the activation of apoptosis or in the impairment of immunosurveillance, two mechanisms that lead to a higher lung cancer risk." (PMID 23577098, 2013). "Molecular analysis is commonly used in samples obtained by EBUS-TBNA from patients with lung cancer, where they have been used to distinguish different types of non-small-cell lung cancer and to detect epidermal growth factor mutations and the EML4-ALK fusion gene." (PMID 23196318, 2013). "To explore whether TWIST1 is a prerequisite for EGF induced EMT in EGFR mutated lung cancer cells, we confirmed that long time EGF treatment (10 days) did not generate an EMT in HCC827 TWIST1 negative cells." (PMID 22272264, 2012). "Current strategies to treat cancer is mainly driven by identifying genetic changes (e.g., EGFR, epidermal growth factor mutations in lung cancer), but recent evidence suggests that epigenetic plasticity together with genetic lesions also drives tumor progression." (PMID 21085674, 2010). "Thus, we hypothesized that EGF+61 A>G SNP might be associated with a response to first‐generation TKIs in lung cancer." (PMID 32881389, 2020). "In order to investigate whether TWIST1 could determine morphological changes in EGFR mutated tumors we analyzed the effect of TWIST1 expression in vitro and showed that in EGFR mutated lung cancer cells, EGF pathway stimulation and TWIST1 cooperated to induce an EMT and the associated cell mobility." (PMID 22272264, 2012). "Indeed, exaggerated EGF tyrosine kinase activity is a probable cause for lung cancer." (PMID 19529782, 2009). "In lung cancer, EGF-induced nuclear translocation of SHCBP1 enhances β-catenin transactivation, increasing cellular stemness in non-small cell lung cancer (NSCLC)." (PMID 40799237, 2025). "Small cell transformation is an example of resistance to tyrosine kinase inhibition in epidermal growth factor mutant lung cancer." (PMID 41149474, 2025). "Some studies have reported that higher degree of sialylation and phosphorylation interactively regulate EGFR dimerization and activation in TKI-resistant EGFR mutant cells and sialidase can increase EGFR dimerization upon EGF treatment in lung cancer cells." (PMID 40154885, 2025). "Lung cancer development involves mechanisms like reduced EGFR/EGF ubiquitination driving cancer cell behaviors and immune evasion via loss of PD‐1/PD‐L1 ubiquitination." (PMID 40313038, 2025). "The identification of epidermal growth factor receptor (EGFR) overexpression in lung cancer led to the creation of CIMAvax-EGF." (PMID 40922740, 2025). "Recent understanding reveals that boehmenan, a constituent of CFI, induces apoptosis in lung cancer cells by regulating epidermal growth factor (EGF) dependent pathways." (PMID 40417000, 2025). "Despite economic challenges, Cuba achieved remarkable progress with CIMAvax-EGF, a therapeutic vaccine for lung cancer." (PMID 40872964, 2025). "This retrospective review focuses on genomic alterations at various time points observed in patients with epidermal growth factor mutant lung cancer who underwent histologic transformation." (PMID 41149474, 2025). "Functionally, PYCR1-KO lung cancer cells showed a significant reduction in cancer progression in response to EGF stimulation." (PMID 41254241, 2025).
lung carcinoma (continued). "Using human and mouse lung epithelial cell lines, we observed that recombinant (r)EREG induced wound healing and increased cell growth at levels similar to EGF, thus supporting EREG as a marker of this hallmark for early-stage lung cancer." (PMID 39771097, 2024). "For instance, AQP3-mediated H2O2 transport was shown to be involved in EGF-induced cell signaling in squamous cell carcinoma (A431) and lung cancer (H1666) cell lines, and AQP3 blockage suppresses the cell response to EGF." (PMID 39125952, 2024). "CIMAvax-EGF is being administered to advanced lung cancer patients who are immunocompromised on account of their older age, the cancer itself, and the previous platinum-based chemotherapy, in most cases." (PMID 38304035, 2023). "This has moved beyond theory for some lung cancer patients as, in Cuba, a vaccine that raises antibodies against EGF (CimaVax‐EGF) is approved for use as a maintenance therapy in advanced NSCLC." (PMID 37795653, 2023). "Considering the importance of the EGF signaling pathway in the development of lung cancer, does LAD1 participate in EGF signaling to regulate lung cancer development?" (PMID 36770773, 2023). "As expected, EGF treatment decreased the effect of ALKi on cell viability in all tested ALK‐rearranged lung cancer cell models." (PMID 36423211, 2023). "Under the influence of EGF, Sortilin appears to promote clathrin-dependent internalization in lung cancer." (PMID 37576898, 2023). "ALDH1A1 drives the maintenance of a CSC‐like subgroup of lung cancer cells and transcriptionally enhances EGF expression, promoting LUSC tumourigenesis." (PMID 36504325, 2022). "First, we compared the mRNA levels of common EGFR ligands in lung cancer (HB-EGF, EGF, TGF-α, BTC, AREG, and EREG) by using the gene expression dataset GSE30219, GSE3141, and GSE50081." (PMID 36439487, 2022). "The EGF/EGFR signaling pathway has been reported to regulate DSB repair in lung cancer cells following X-irradiation by promoting both the NHEJ and HR pathways." (PMID 35502895, 2022). "Both AvnA and AvnC did not affect the migration in basal conditions but were effective in reducing A549 cell migration induced by EGF, suggesting that these compounds possess an anti-migratory activity on lung cancer cells." (PMID 35955669, 2022). "Several cancer vaccines are available in clinical therapy, including Melacine for melanoma and Cima Vax EGF for lung cancer." (PMID 36358616, 2022). "Low levels of lamin-A/C in lung cancer cells were maintained in the presence of migratory signaling molecules, such as EGF." (PMID 36012358, 2022). "CD44, CD87, CD117, CD276, Axl, EGF, and Ki67 are the most commonly used markers to identify CSCs in lung cancer." (PMID 36142766, 2022). "In this work we further explored the antitumor potential of Avns by analyzing their effects on lung cancer cells and in EGF driven signaling, representing the engine of lung cancer." (PMID 35955669, 2022). "A therapeutic cancer vaccine (CIMAvax-EGF) developed based on EGF in lung cancer patients showed good tolerability and survival benefit in clinical trials." (PMID 36172369, 2022). "We here investigated the functions and the underlying regulatory mechanisms of the two YAP1 isoforms in the context of EGF‐induced epithelial‐mesenchymal transition (EMT) in non‐small cell lung cancer (NSCLC)." (PMID 35014181, 2022). "Subsequently, we found this double mark was also enhanced by EGF in non–small cell lung cancer A549 and glioblastoma U251 cells." (PMID 35931120, 2022). "EGF concentration in human serum is largely variable, both in healthy and lung cancer patients, but it tends to be higher in patients." (PMID 34211836, 2021). "The EGF signaling axis is critically involved in tumor cell growth in lung cancer and several other cancer types, e.g., prostate cancer." (PMID 33777943, 2021). "In our previous study, the concentrations of EGF were examined in serum samples from 154 healthy donors and 57 patients with lung cancer." (PMID 34804932, 2021).